GCLC (glutamate-cysteine ligase catalytic subunit)
Diseases named in the same sentence as GCLC in open-access papers (continued):
Sharing a sentence is not in itself a finding about the gene and the disease.
colorectal cancer (8 papers, 2020 to 2025). A primary or metastatic malignant neoplasm that affects the colon or rectum. "Next, a CRISPR-Ecas9-engineered GCLC knockout (KO) variant of the colorectal cancer-derived organoid Tor10 (GCLC 24.1) was used and compared to control Tor10 organoids that only expressed Ecas9." (PMID 40204947, 2025). "As well, GCLC has been found to overexpress in liver metastases of colorectal cancer and promotes cancer cell survival." (PMID 32850411, 2020). "The combination of effective GCLC inhibitors, in combination with RRx-001 could have a major impact on the treatment of various aggressive (colorectal) cancer subtypes, including radioresistant rectal cancer." (PMID 40204947, 2025). "However, there was also a report that the increased expression of GCLC and xCT was independent on Nrf2 in colorectal carcinoma cells." (PMID 33505589, 2021). "For instance, MYH9 facilitates the cell EMT and migration of colorectal cancer by activating MAPK/AKT signalling, and promotes cell invasion and radioresistance in head and neck cancer by modulating the cellular ROS levels via activation of the MAPK/Nrf2/GCLC axis." (PMID 37875476, 2023). "The results of immunohistochemical studies showed that GCLC and GSS were higher in colorectal cancer tissue than in normal mucosa." (PMID 38256082, 2024).
endothelial dysfunction (8 papers, 2012 to 2025). In vascular diseases, endothelial dysfunction is a systemic pathological state of the endothelium (the inner lining of blood vessels) and can be broadly defined as an imbalance between vasodilating and vasoconstricting substances produced by (or acting on) the endothelium. "GCLc-deficient ECs exhibit elevated basal and stimulated ROS levels, leading to endothelial dysfunction." (PMID 40232847, 2025). "Specifically, the heme oxygenase-1 (HO-1), NADPH quinone oxidoreductase (NQO-1), glutamate-cysteine ligase catalytic subunit (GCLC), Phospho-Akt (p-Akt), and Phospho-eNOS (p-eNOS) expression levels were enhanced by sinapic acid, easing endothelial dysfunction." (PMID 38611326, 2024). "In conclusion, the results of this study support the notion that in young healthy smokers with endothelial dysfunction, a novel further consequence of increased oxidative stress is an endothelial decrease of Nrf2 and GCLC expression with consequent GSH depletion." (PMID 22272327, 2012). "Sinapic acid alleviated endothelial dysfunction by enhancing HO-1, NQO-1, GCLC, p-Akt, and p-eNOS expression levels, as well as activating Nrf2 nuclear translocation." (PMID 36234721, 2022).
lung adenocarcinoma (7 papers, 2019 to 2025). A carcinoma that arises from the lung and is characterized by the presence of malignant glandular epithelial cells. "High mRNA expression of GCLC in tumor tissue significantly shortens the postoperative recurrence survival period of patients, and potentially can predict cisplatin resistance in patients with lung adenocarcinoma." (PMID 36203872, 2022). "Also, high mRNA expression of GCLC in cancer tissue has been suggested as a potential predictor of cisplatin resistance in lung adenocarcinoma patients." (PMID 32327612, 2020).
glioma (5 papers, 2017 to 2023). A benign or malignant brain and spinal cord tumor that arises from glial cells (astrocytes, oligodendrocytes, ependymal cells). "Previous data showed that intratumoral thymidine from necrotic cells inhibited GCLC activity and that GCLC expression was upregulated in IDH1-mutated compared to IDH1 wild-type glioma." (PMID 34568059, 2021). "The expression levels of risk factors IL4I1, SMS, and ADI1 in high-grade gliomas were higher than those in lower‐grade gliomas, while the protein expression levels of protective factor GCLC, MSRB2, MTAP and MPST were exactly the opposite." (PMID 38057821, 2023). "In our study, GSS (glutathione synthetase) and GCLC had similar functions in synthesising glutathione, but they play opposite roles in promoting and inhibiting glioma progression." (PMID 38057821, 2023). "Based on the expression of almost 600 patients, we found that the levels of CBS and GCLc were significantly upregulated in IDHm compared to IDHwt gliomas supporting a higher activation of the transsulfuration pathway." (PMID 29054837, 2017). "The increased expression of CBS and GCLc in IDHm gliomas supports the idea that IDHm tumors may preferentially utilize the transsulfuration pathway for GSH synthesis." (PMID 29054837, 2017). "Among IDHm gliomas, CBS expression was higher in IDHm‐1p/19q co‐deleted gliomas compared to IDHm without 1p/19q co‐deletion, contrary to GCLc." (PMID 29054837, 2017).
Hyperglycemia (5 papers, 2009 to 2023). An increased concentration of glucose in the blood. "More so than any other gene, reduced GCLC mRNA and protein expression were found to be associated with forced hyperglycemia in PDAC." (PMID 37380658, 2023). "Inhibition of GCLC phenocopies the suppressive effect of forced hyperglycemia in mouse models of PDAC, while rescuing this pathway mitigates anti-tumor effects observed with chemotherapy and high glucose." (PMID 37380658, 2023). "Significantly, the increase in GCL activity and GSH synthesis via insulin signaling and activation of the PI3K/Akt/mTOR/Nrf2/GCLc pathway prevented hyperglycemia-induced endothelial apoptosis." (PMID 22745639, 2012). "As it has been observed that broilers are insulin and hyperglycemia resistant, we proposed that GCLC would be a potential regulator in hyperglycemia resistance process for broiler chickens." (PMID 19232135, 2009). "While many antioxidant genes were upregulated in hyperglycemic mice, perhaps due to a compensatory response, further examination of transcriptome changes indicated the catalytic subunit of glutamate-cysteine ligase (GCLC) was considerably reduced in KPC orthotopic tumors under hyperglycemia." (PMID 37380658, 2023).
liver cancer (5 papers, 2015 to 2024). An epithelial or non-epithelial malignant neoplasm that arises from the liver. "The rate-limiting enzyme of glutathione synthesis in liver cancer is the glutamate-cysteine ligase catalytic subunit (GCLC), which is downregulated by c-Myc, lowering GSH bioavailability." (PMID 36483029, 2022). "High GCLC levels were found in HCC tumor tissues and were associated with poor overall survival (OS) and disease-free survival (DFS) in patients after curative treatment, while MYC-driven inhibition of GCLC through miR-18a increased the sensitivity of liver cancer cells to oxidative stress." (PMID 39061847, 2024). "C-Myc-regulated miR-18a downregulates the glutamate-cysteine ligase catalytic subunit (GCLC), the rate-limiting enzyme of glutathione synthesis in liver cancer, reducing the availability of GSH." (PMID 35348905, 2022). "We postulate that in the setting of low GCLC expression, and consequently low GSH production that some MYC-driven tumors, such as liver cancers, may be especially sensitive to exogenous oxidative stress." (PMID 28443280, 2017). "In addition, miR-18a was significantly elevated in human HCC compared to non-tumor liver, was negatively correlated with GCLC expression in human HCC, and was positively correlated with alpha-fetoprotein (AFP) expression, which is associated with aggressive liver cancer." (PMID 28443280, 2017).
ovarian carcinoma (5 papers, 2012 to 2025). A malignant neoplasm originating from the surface ovarian epithelium. "For instance, ARID1A-deficient ovarian cancers demonstrate synthetic lethality upon GCLC depletion, underscoring its therapeutic potential." (PMID 41333220, 2025). "In fact, the inhibition of GCLC significantly decreased GSH in ARID1A-deficient TOV21G ovarian cancer cells, leading to apoptosis (due to increased ROS levels)." (PMID 38203758, 2024). "It was suggested that targeting glutamate-cysteine ligase catalytic subunit (GCLC) could be an effective therapeutic strategy for ARID1A-deficient ovarian cancers." (PMID 41333220, 2025). "Research has shown that the glutamate-cysteine ligase catalytic subunit (GCLC) could serve as a new therapeutic target for ARID1A-deficient ovarian cancer cells." (PMID 39609317, 2024). "Thus, ARID1A-deficient ovarian cancers may be susceptible to drugs targeting GCLC since their efficiency is enhanced by a low SLC7A11 expression that keeps GSH content at low levels." (PMID 38203758, 2024). "In ovarian cancer cell lines that have high expression of GCLC, the expression of GCLC is predicted to be positively regulated by hsa-miR-133a and negatively by hsa-miR-140-3p." (PMID 31210841, 2019).
gastric cancer (4 papers, 2023 to 2025). A primary or metastatic malignant neoplasm involving the stomach. "We first analyzed the protein levels of NSUN2 and GCLC in six gastric cancer cell lines by western blotting analysis, and found a relatively higher level of NSUN2 in all cell lines, except SNU-1." (PMID 39742570, 2025). "For instance, actin-like 6 A (ACTL6A) promotes GSH synthesis by elevating the expression of the rate-limiting enzyme GCLC, thereby safeguarding gastric cancer cells from ferroptosis." (PMID 39548421, 2024). "Here, the authors 2 find elevated expression of ACTL6A in gastric cancer promotes glutathione synthesis by regulating 3 GCLC expression to suppress ferroptosis." (PMID 37443154, 2023). "We further demonstrated that GCLC mRNA is a target of lactylated NSUN2, which coordinately regulates the lipid peroxidation level and the phenotype to ferroptosis resistance in gastric cancer cells." (PMID 39742570, 2025). "The activated GCLC induces higher level of intracellular GSH accompanied by decreased lipid peroxidation and resistant phenotype to ferroptosis induction by doxorubicin (Dox) in gastric cancer cells." (PMID 39742570, 2025).
liver fibrosis (4 papers, 2016 to 2025). "The study aimed to clarify the role and molecular mechanism of glutamate-cysteine ligase catalytic subunit (GCLC) in modulating Hepatitis C virus (HCV)-related liver fibrosis." (PMID 33015132, 2020). "Then we further explored the potential mechanism of GCLC in the development of HCV-related liver fibrosis." (PMID 33015132, 2020). "In conclusion, GCLC is a negative regulatory factor in the progression of HCV-related liver fibrosis." (PMID 33015132, 2020). "Long-term ingestion of APAP can induce liver fibrosis, while andrographolide has been shown to alleviate APAP-induced liver fibrosis in mice by activating Nrf2 and upregulating the expression of downstream genes glutamate-cysteine ligase (GCLC and GCLM) and heme oxygenase-1 (HO-1)." (PMID 40959446, 2025). "The results indicated that GCLC might participate in the pathogenesis of HCV-related liver fibrosis." (PMID 33015132, 2020). "Therefore, the aim of this study was to clarify the role and potential mechanism of GCLC in the activation of HSCs and hepatic fibrosis induced by HCV infection." (PMID 33015132, 2020). "Our data suggested that aberrant mRNAs might contribute to the progression of HCV-related hepatic fibrosis, among that glutamate-cysteine ligase catalytic subunit (GCLC) was significantly differentially expressed." (PMID 33015132, 2020). "Overexpression of GCLC in LX-2 cells could increase GSH level and decrease ROS production, which suppressed ER stress and reduced hepatic inflammation and fibrosis, and inhibition of GSH biosynthesis by L-BSO could overt the effect of GCLC on liver fibrosis." (PMID 33015132, 2020). "And overexpression of GCLC may ameliorate the development of liver fibrosis in HCV patients through decreasing ROS production, increasing the GSH level, and also attenuate ER stress and inflammation." (PMID 33015132, 2020). "Emerging evidence showed that GCLC was involved in the pathogenesis of liver fibrosis." (PMID 33015132, 2020). "Several reports implicated knockdown of GCLC exacerbated bile duct ligation-induced liver injury and fibrosis, which suggested that cellular GSH supplement provide a novel means to suppress hepatic fibrosis." (PMID 27081693, 2016). "Thus, antioxidative stress therapy through overexpressing GCLC might be a new treatment target of HCV-related liver fibrosis." (PMID 33015132, 2020). "Expression of many antioxidant proteins such as glutathione S-transferases (GSTs), and glutamate-cysteine ligase catalytic subunit (GCLC), can lead to a rapid recovery of glutathione levels, which may represent a useful strategy to prevent liver damage after liver fibrosis stimulators insults." (PMID 27081693, 2016). "The mRNA and protein expression of GCLC, endoplasmic reticulum (ER) stress markers, and inflammatory and fibrogenic factors were detected in liver tissues from patients with HCV-related hepatic fibrosis and HCV core protein-expressing LX-2." (PMID 33015132, 2020). "And overexpression of GCLC in vivo could significantly decrease collagens in CCL4-induced and pig serum-induced liver fibrosis model." (PMID 33015132, 2020). "Patients with HCV-related hepatic fibrosis showed increased serum ALT levels and liver fibrosis degree, accompanied by a parallel increase in the expression of hepatic α-SMA and COL1, and a dramatically decreased expression of hepatic GCLC." (PMID 33015132, 2020). "GCLC was a negative regulatory factor in the development of HCV-related liver fibrosis and might be a potential therapeutic target for liver fibrosis." (PMID 33015132, 2020). "Also, the RT-PCR and Western blot analysis verified an increase in α-SMA and COL1 expression and a decrease in GCLC mRNA and protein expression in HCV-related hepatic fibrosis." (PMID 33015132, 2020). "Hence, GCLC may function as a novel anti-fibrosis factor and be a potential therapeutic target for HCV-related liver fibrosis." (PMID 33015132, 2020).
liver fibrosis (continued). "However, CHOP as a pro-apoptosis gene was also increased in activated HSC, and overexpression of GCLC could decrease CHOP expression, which might contribute to the apoptosis of activated HSC, leading to ameliorate liver fibrosis." (PMID 33015132, 2020). "And in patients with HCV-related liver fibrosis, GCLC was notably decreased in plasma and liver tissue, and it also decreased in activated HSC induced by conditioned medium derived from LO2-core and HepG2-core cell lines, which indicated that antioxidant role of GCLC was disturbed." (PMID 33015132, 2020). "In contrast, the expressions of GCLC, GCLM, NQO1, and HO-1 in the liver of the model group were significantly increased by YJSB, suggesting that YJSB might improve the antioxidant capacity of the redox system in rats, reduce oxidative stress, and interfere with the development of hepatic fibrosis." (PMID 37229248, 2023).
acute myeloid leukemia (3 papers, 2022 to 2025). Acute myeloid leukemia (AML) is a group of neoplasms arising from precursor cells committed to the myeloid cell-line differentiation. "CRISPR knockout studies further demonstrate that GCLC is essential for the survival of acute myeloid leukemia (AML) cells but less critical for normal hematopoietic cells, highlighting its selective therapeutic potential." (PMID 41333220, 2025).
chronic obstructive pulmonary disease (3 papers, 2017 to 2024). A chronic and progressive lung disorder characterized by the loss of elasticity of the bronchial tree and the air sacs, destruction of the air sacs wall, thickening of the bronchial wall, and mucous accumulation in the bronchial tree. "However, epigenetic silencing of GCLC gene by hypermethylation of its promoter region was observed in human patients of chronic obstructive pulmonary disease." (PMID 38936463, 2024).
colitis (3 papers, 2020 to 2023). Inflammation of the colon. "The literature also reported that quercetin alleviated DSS-induced murine colitis by increasing the expression of the glutamate-cysteine ligase catalytic subunit (GCLC) and serum glutathione level." (PMID 37298531, 2023). "In this study, we have specifically verified that targeted antioxidant genes of the Nrf2 pathway, GCLC and GPX, were upregulated after DMF treatment in mice with DSS-induced colitis." (PMID 32344663, 2020).
COVID-19 (3 papers, 2020 to 2023). A disease caused by infection with severe acute respiratory syndrome coronavirus 2. "In regard to the targeting of GSH biosynthesis via proteolytic degradation of GCLC (Section 3.1.3), the rate limiting enzyme for GSH biosynthesis, it must be noted that there have been a number of reports implicating GSH deficits as a major factor in COVID-19 severity and pathogenesis." (PMID 36978807, 2023).
diabetic retinopathy (3 papers, 2021 to 2025). "Keap1 prevents Nrf2 translocation from the cytosol to the nucleus to bind with ARE4, thereby downregulating the transcription of GCLC and largely attenuating the biosynthesis of GSH, indicating that the Nrf2-Keap1-GCLC pathway plays an important role in diabetic retinopathy." (PMID 35340204, 2022). "Additionally, the protein expressions of heme oxygenase‐1 (HO‐1), glutamate‐cysteine ligase catalytic subunit (GCLC), and NAD(P)H dehydrogenase (quinone 1) (NQO1) were all significantly reduced in mice with diabetic retinopathy, and all were significantly restored by the supplement of GSP." (PMID 41409191, 2025). "Similar to our previous findings in a diabetic retinopathy model, LG treatment did not result in an increase of HO-1, SOD-2 or GCLC expression, indicating that the antioxidant effect of LG is likely to be due to its radical scavenging properties." (PMID 34393798, 2021).
Insulin resistance (3 papers, 2023 to 2024). Increased resistance towards insulin, that is, diminished effectiveness of insulin in reducing blood glucose levels. "Meanwhile, previous studies reported that impaired antioxidant systems in adipocytes, such as the fat-specific deletion of glutathione peroxidase 4 (GPX4) or glutamate-cysteine ligase (GCLC), led to insulin resistance 58,59." (PMID 38653240, 2024).
neuroblastoma (3 papers, 2017 to 2022). Neuroblastoma (NB) is the most common solid, extracranial childhood tumor. "Interestingly, in neuroblastoma the elevation of glutathione occurred despite a downregulation in GCLC mRNA levels." (PMID 28443280, 2017). "Thus, in both MYC driven liver and neuroblastoma models GCLC expression is suppressed, though the effects on glutathione production appear to be contextually dependent." (PMID 28443280, 2017).
Obesity (3 papers, 2014 to 2019). Accumulation of substantial excess body fat. "It had been reported that obesity mothers who carried mutant genotype AC for glutamate-cysteine ligase, catalytic subunit (GCLC) gene (rs6458939) significantly increased the risk of conotruncal defects (CTDs) in infants, compared with those obesity mothers who carried the CC genotype." (PMID 31360700, 2019).